TRPV1 (transient receptor potential cation channel subfamily V member 1)
Diseases named in the same sentence as TRPV1 in open-access papers (continued):
Sharing a sentence is not in itself a finding about the gene and the disease.
autoimmune disease (8 papers, 2012 to 2026). A disorder resulting from loss of function or tissue destruction of an organ or multiple organs, arising from humoral or cellular immune responses of the individual to their own tissue constituents. "TRPV1 was shown to be implicated in neurogenic inflammation, neuropathic pain, autoimmune disorders, cancer and immune cells functioning." (PMID 31681615, 2019). "This review provides an overview of the structure, biological functions, and implications of TRPV1 in autoimmune diseases." (PMID 41569118, 2026). "A comprehensive understanding of TRPV1’s structure, function, and role in autoimmune diseases lays the foundation for future studies and the development of innovative therapies targeting this channel." (PMID 41569118, 2026). "Understanding the structure, function, and implications of TRPV1 in autoimmune diseases provides a foundation for future research and the development of innovative therapeutic strategies." (PMID 41569118, 2026). "First, TRPV1 is a possible treatment for a wide range of illnesses, such as inflammation, cancer, and autoimmune diseases." (PMID 36111960, 2022). "Further studies are therefore necessary to clarify the role of TRPV1 and neuropeptides in inflammation and autoimmune diseases." (PMID 24280677, 2012). "Further studies are required to clarify the role of TRPV1 and neuropeptides, which are released because of TRPV1 activation in inflammation and autoimmune diseases." (PMID 24280677, 2012). "Furthermore, we will explore the relevance of TRPV1 in drug development for the treatment of autoimmune disorders." (PMID 41569118, 2026). "Further studies are necessary to clarify the role of TRPV1 in autoimmune diseases." (PMID 24280677, 2012). "The data list generated by Genomatix show that TRPV1 (along with other genes) participates in diseases such AKI, CNS disorder, inflammatory disorders, central nervous system sensitization and autoimmune diseases." (PMID 31417109, 2019). "While T1D is traditionally conceptualized as a peripheral autoimmune disease, increasing evidence implicates CNS dysfunction—particularly involving TRP channels such as TRPV1 as a critical mediator of cognitive decline, autonomic dysregulation, and mood disorders in affected individuals." (PMID 41463571, 2025). "Unlike B cells, TRPV1 implication in T cells is a little bit more extensive, especially in the context of inflammatory and autoimmune disorders." (PMID 31681615, 2019).
COVID-19 (8 papers, 2020 to 2026). A disease caused by infection with severe acute respiratory syndrome coronavirus 2. "Since most COVID-19 symptoms are associated with pathways controlled by TRPV-1, we, therefore, expect that the people with 585I, 91S, and 315 M will be more susceptible to adverse effects of COVID-19 infection." (PMID 34805220, 2021). "Furthermore, TRPV1/A1, implicated in the cough reflex, was confirmed in COVID-19 through induced cough challenges, demonstrating rapid relief with TRPA1/V1 agonists (green tea, curcumin, ginger, red pepper)." (PMID 38827576, 2024). "The pro-inflammatory role of TRPV-1 in the elderly might contribute to aggravate the incidence of COVID-19 fatality associated with older patients, especially people over 65-years-old." (PMID 34805220, 2021). "The analysis of the polymorphic site of the TRPV-1 for deciphering COVID-19 susceptibility could be the key to identify the more vulnerable individuals and those at higher risk for severe disease." (PMID 34805220, 2021). "In summary, TRPV-1 genetic variants and their modulation by air pollutants may play a central role in infection and effects of COVID-19." (PMID 34805220, 2021). "In another direction of thought, harmful stimuli activate TRPV1 and increase the release of SP and pro-inflammatory cytokines, which exacerbate the symptoms of patients infected with COVID-19." (PMID 37402746, 2023). "Furthermore, activation of TRPV-1 increases the release of several pro-inflammatory molecules, for example neuropeptide substance P (sP) and cytokines such as interleukin 6 (IL-6), exactly the molecules that have been implicated in the pathophysiological events associated with COVID-19." (PMID 36613152, 2023). "While the direct interaction of SARS-CoV-2 with TRPV1/A1 receptors awaits investigation, increased levels of endogenous mediators during COVID-19, particularly elevated PGE2 in severe cases and dysregulated BK signaling in patients with COVID-19 pneumonia, suggest potential involvement." (PMID 38827576, 2024). "The pathophysiology in COVID-19 patients is similar to the effects generated by TRPV-1 stimulation." (PMID 39835320, 2024). "Notably, various COVID-19 symptoms align with TRPV1/A1 channels, reinforcing the likelihood of their role in the detected cardiac autonomic imbalance." (PMID 38827576, 2024). "Furthermore, our group recently studied the involvement of TRPV-1 in COVID-19 by modulating SARS-CoV-2 binding and the consequent inflammatory conditions." (PMID 36613152, 2023). "Furthermore, the pathophysiology in COVID-19 patients is similar to the effects generated by TRPV-1 stimulation." (PMID 34805220, 2021). "Yet, TRPV1+ nociceptors could also become more pro-inflammatory with age, in which case it would make sense to block afferent signaling from TRPV1 sensory neurons in elderly COVID-19 patients." (PMID 34975876, 2021). "Therefore, TRPV-1 desensitization could be beneficial for the treatment of COVID-19 and its symptoms, as well as back pain that often accompanies COVID-19 infection." (PMID 39835320, 2024). "TRPA1 and TRPV1 may provide a breakthrough in the treatment of symptoms of COVID-19." (PMID 37402746, 2023). "Therefore, inhalation exposures to high levels of pollution during SARS-CoV-2 infection could worsen the outcome of COVID-19 in affected patients, directly modulating the activity of TRPV-1." (PMID 34805220, 2021). "Furthermore, activation of TRPV-1 boosts the release of various pro-inflammatory molecules, including neuropeptides substance P (sP) and cytokines such as interleukin 6 (IL-6), the same involved in the pathophysiological events affecting the COVID-19." (PMID 34805220, 2021). "The upregulation and subsequent modulation of TRPV-1 by lung inflammation products, i.e., PGE2, and BK, during and following airways viral infections, including COVID-19, may explain hypersensitivity of the cough reflex during the period of illness and after COVID-19 (post-viral vagal neuropathy)." (PMID 34805220, 2021).
Hepatic steatosis (8 papers, 2016 to 2025). Steatosis is a term used to denote lipid accumulation within hepatocytes. "Our recent study demonstrated that chronic-binge EtOH-mediated increases in circulating OXLAMs and TRPV1 levels in mice were associated with hepatic steatosis, inflammation, and injury." (PMID 26751488, 2016). "TRP channels exhibit both pro- and anti-hepatic steatosis activity, evidenced by the observation that loss of TRPC5, TRPV1, and TRPM2 protected, whereas loss of TRPV4 aggravated hepatic steatosis." (PMID 39871879, 2024). "In contrast, TRPV1−/− mice exhibited markedly reduced levels of both PPARα and PGC-1α, consistent with the severe hepatic steatosis observed in histological analyses (H&E and Oil Red O staining)." (PMID 40864772, 2025).
interstitial cystitis (8 papers, 2008 to 2025). A rare chronic debilitating urogenital disease characterized by urinary frequency, urgency, and pelvic pain. "Only TRPV1 expression was significantly associated with the O’Leary–Sant symptom score (OSS), interstitial cystitis symptom index (ICSI), and interstitial cystitis problem index (ICPI)." (PMID 36614264, 2023). "TRPV1-immunoreactive nerve fibers are involved in the pathogenesis of interstitial cystitis/painful bladder syndrome (IC/PBS)." (PMID 36135835, 2022). "Previous studies have shown a significant increase of TRPV1-IR nerve fibers in inflammatory conditions that elicit pain, such as painful bladder syndrome and vulvodynia, and are believed to involve NGF." (PMID 18267041, 2008).
pneumonia (8 papers, 2021 to 2025). An acute, acute and chronic, or chronic inflammation focally or diffusely affecting the lung parenchyma, caused by an infection in one or both of the lungs (by bacteria, viruses, fungi, or mycoplasma.). "TRPV1-expressing peripheral sensory neurons have been implicated in the host’s response to pneumonia, and enteric infection with Citrobacter." (PMID 35610647, 2022). "We evaluated the influence of TRPV1 on the dynamics of S. pneumoniae nasal infection between TRPV1 KO and WT mice." (PMID 40823821, 2025). "Prior studies focused on the role of peripheral nervous system TRPV1 in modulating inflammation and pneumonia." (PMID 35610647, 2022). "Moreover, a most recent study also showed that common introgression signals of alleles ADCY3, TRPV1, and PADI2 genes from wild relatives enhanced climatic adaptation and resistance to pneumonia in domestic sheep." (PMID 39725653, 2024). "Likewise, in a Staphylococcus aureus mouse model of lethal pneumonia, neutrophil recruitment and functions were suppressed by TRPV1+ nociceptors, as mice lacking TRPV1+ fibers exhibited a higher percentage of neutrophils in the lungs 6h post infection, a lower bacterial burden and better survival." (PMID 37006298, 2023). "Mice lacking TRPV1 or TRPV4 channels, however, showed moderate to severe pneumonia 48 h after the super-infection of the pneumococcus." (PMID 34804016, 2021).
pyrexia (8 papers, 2012 to 2025). "In the present study, we demonstrated that TRPV1 KO mice exhibited prominent hyperthermia and spent less time of heat loss behaviors upon warm ambient exposures." (PMID 32472067, 2020). "Fever induced by LPS was further aggravated by PKA/PKC antagonists through the inhibition of p-TRPV1, linking PKA signaling to thermoregulation." (PMID 41327470, 2025). "Hyperthermia also occurred in WT mice that received intracerebroventricular injections of the TRPV1 antagonist AMG9810 upon exposure to 35.0 °C." (PMID 39933439, 2025). "Hyperthermia also occurs in WT mice that received intracerebroventricular injection of TRPV1 antagonist AMG9810 upon exposure to 35.0 °C." (PMID 32472067, 2020). "Hyperthermia was also observed in WT mice when they received i.c.v. injection of TRPV1 antagonist AMG9810." (PMID 32472067, 2020). "Moreover, a study to explore the possible mechanism of Dahuang’s antipyretic effect on yeast-induced pyrexia rats found that Dahuang reduced rectal temperature; importantly, it inhibited the fever-induced expression of TRPV1 and enhanced TRPM8 in hypothalamus and DRG." (PMID 33542688, 2020). "By replicating the zebra fish fever model, it was found that TRPV1, TRPV4, and PGE2 co-regulated the development of fever, and the decreased expression of TRPV4 contributed to the generation of fever." (PMID 40356990, 2025). "A previous study suggested that FT-A significantly downregulated TRPV1 expression in the hypothalamus and DRG of yeast-induced pyrexia mice." (PMID 33013395, 2020). "Hyperthermia is not observed in the systemic TRPV1 KO mice, but occurs with acute inhibition in WT mice treated with TRPV1 antagonists." (PMID 39933439, 2025). "In a model of yeast induced pyrexia, administration of APAP evoked a marked hypothermia in wildtype and Trpv1−/− mice, but only restored normal body temperature in Trpa1−/− and Trpa1−/−/Trpv1−/− mice." (PMID 26227887, 2015).
allergic contact dermatitis (7 papers, 2012 to 2023). An inflammatory skin condition caused by an immune response to direct contact between the skin and an allergen. "TRPV1 was vital in the development of chronic itch induced by dry skin and allergic contact dermatitis (ACD)." (PMID 28701920, 2017). "Furthermore, our study indicates that TRPV1 plays a pivotal role in the chronic itch evoked by dry skin and allergic contact dermatitis (ACD)." (PMID 28701920, 2017). "In addition, our recent work found that IL-33 released by keratinocytes can activate peripheral sensory neurons via promoting Ca2+ influx through TRPA1/TRPV1 channels in ST2 dependent mechanism, resulting in potentiation of skin inflammation and pruritus in a mouse allergic contact dermatitis model." (PMID 33204337, 2020).
Erythema (7 papers, 2016 to 2026). Redness of the skin, caused by hyperemia of the capillaries in the lower layers of the skin. "For instance, TRPV1 agonists can cause pain and/or erythema before desensitization becomes effective, and TRPV1 antagonists usually present lower efficacy compared to TRPV1 agonists and can cause hyperthermia." (PMID 27367653, 2016). "However, potent TRPV1 agonist capsaicin causes an initial adverse effect of pungency and even an 8% capsaicin dermal patch can lead to erythema and pain at the site of application." (PMID 36080196, 2022). "Transient receptor potential vanilloid 1 (TRPV1) channels are critical mediators of cutaneous allergic inflammation, contributing to pruritus, erythema, and hypersensitivity in allergic skin disorders." (PMID 41511362, 2026). "Dysregulation of TRP channel activity, particularly TRPV1 and TRPA1, has been shown to induce neurogenic inflammation, erythema, and irritation, which are hallmark features of skin toxicity." (PMID 41373824, 2025). "Moreover, in vitro studies have shown that capsaicin exposure triggers TRPV1-mediated Ca2+ influx in keratinocytes, leading to the release of inflammatory cytokines such as IL-6, IL-8, and TNF-α, which are linked to erythema, capillary dilation, and pain." (PMID 40041491, 2025). "The experimental cream alleviates symptoms such as pruritus, burning, pain, and erythema, increases CPT values, and lowers CAT scores, possibly due to the effect of salvia miltiorrhiza root extract in reducing TRPV1 expression." (PMID 40736038, 2025). "In general, the activation of TRPV1 stimulated the sensory neurons C fibers to release vasoactive peptides, such as CGRP and SP, leading to vasomotor dysfunction, and high neurovascular reactivity manifesting as paroxysmal flushing, persistent erythema and telangiectasia." (PMID 36874007, 2023).
oropharyngeal dysphagia (7 papers, 2014 to 2026). "A randomized controlled trial reported that chronic supplementation of a TRPV1 agonist (capsaicin) in aged patients with oropharyngeal dysphagia increased the salivary substance P levels as well as improving swallowing function." (PMID 32867366, 2020). "In another study in oropharyngeal dysphagia patients, a TRPV1 agonist (capsaicinoid, 150 μM) had a better therapeutic effect on improving swallowing compared with a TRPM8 agonist (menthol, 1 mM or 10 mM)." (PMID 30567389, 2018). "Recent studies in patients with oropharyngeal dysphagia reported that addition of a natural capsaicinoid (a TRPV1 agonist, 150 μM) to the alimentary bolus improved the efficacy of swallowing and reduced the prevalence of pharyngeal residues and penetrations of bolus particles into the larynx." (PMID 30567389, 2018). "In our research, TRPV1 is a promising target to treat oropharyngeal dysphagia, a major complaint among the elderly and patients with neurological diseases, and one characterized by pharyngeal and laryngeal sensory deficits and delayed and prolonged swallow response." (PMID 24688365, 2014). "Previous studies have found that capsaicinoids (TRPV1 agonists) and piperine (TRPA1 and TRPV1 agonists) improve the swallowing response in patients with oropharyngeal dysphagia." (PMID 41548911, 2026). "In conclusion, our systematic review found that TRPV1, TRPA1 and TRPM8 agonists have beneficial effects for patients with neurogenic oropharyngeal dysphagia when compared to placebo interventions." (PMID 34337829, 2022). "The stimulation of swallowing-related regions with a dual TRPV1 and TRPA1 agonist, piperine, has been observed to improve swallowing function in patients with oropharyngeal dysphagia." (PMID 32867366, 2020). "Furthermore, in clinical studies, TRPV1, TRPA1, and TRPM8 agonists improved the efficacy, safety, and physiology of swallowing in patients with oropharyngeal dysphagia." (PMID 36909278, 2023). "The effects of chronic TRPV1 agonist ingestion on swallowing have been investigated both in healthy participants without oropharyngeal dysphagia and in patients with oropharyngeal dysphagia with different etiologies." (PMID 32867366, 2020).
osteoporosis (7 papers, 2015 to 2025). A condition of reduced bone mass, with decreased cortical thickness and a decrease in the number and size of the trabeculae of cancellous bone (but normal chemical composition), resulting in increased fracture incidence. "Our previous studies using an animal model of OVX-induced osteoporotic pain suggest that treatment of osteoporosis is useful for osteoporotic pain associated with osteoclast activity and TRPV1 stimulation." (PMID 33322156, 2020). "TRPV1 is a member of the Ca2+ permeable cation channel subfamily, and pharmacological inhibition of TRPV1 prevents ovariectomy-induced bone loss, which makes TRPV1 a potential target for osteoporosis." (PMID 28225019, 2017). "It has been reported that the mechanism by which ALN improves HRQOL is by improving pain associated with osteoporosis through inhibition of TRPV1, and, furthermore, an RCT showed that ALN has a stronger analgesic effect than calcitonin in women with postmenopausal osteoporosis." (PMID 40745050, 2025). "These molecules are not psychoactive and therefore constitute a good therapeutic candidate in transitional studies that aim to validate the clinical use of CB2 and TRPV1 agonists in osteoporosis treatment." (PMID 31003519, 2019). "In conclusion, our results highlight new mechanistic understanding of precocious osteoporosis in DM and open potential therapeutic avenues, such as TRPV1 antagonists, for treatment of bone pathology in patients with DM." (PMID 27468810, 2016). "Blocking TRPV1 improves pain-like behavior in the murine model of osteoporosis, but whether this occurs as a result of inhibition of proton mediated activation of TRPV1 is not entirely clear." (PMID 28955292, 2017). "Thus, given their inhibitory effect on osteoclast activation, TRPV1 antagonists may represent an alternative strategy for the treatment of osteoporosis." (PMID 27468810, 2016). "Based on all this evidence, an enhanced activation of TRPV1 and CB1 may be responsible for osteoclast activation and for bone resorption in osteoporosis." (PMID 31003519, 2019).